CRP (C-reactive protein)
Diseases named in the same sentence as CRP in open-access papers (continued):
Sharing a sentence is not in itself a finding about the gene and the disease.
malnutrition (continued). "For the purpose of estimating the inflammatory process accompanying both the disease and malnutrition, an analysis of the C-reactive protein (CRP) in serum is used." (PMID 37111024, 2023). "On admission, ESR and CRP were elevated in all patients and malnutrition (serum albumin <3.2g/dl) was observed in five (33.3%) individuals preoperatively." (PMID 36629717, 2023). "Firstly, a higher level of inflammation indicated high levels of cytokines such as IL-1, and IL-6, tumor necrosis factor-alpha and CRP, which greatly accelerates the consumption of nutrition, leading to malnutrition and the progression of CRC." (PMID 37063910, 2023). "The GLIM established a consensus for the identification and endorsement of criteria for the diagnosis of malnutrition in clinical settings including supportive proxy measures of inflammation, such as CRP, albumin, or pre-albumin." (PMID 35807934, 2022). "We found increased levels of CRP in severe malnutrition compared to both non- and moderately malnourished patients, whereas no other inflammatory markers differed." (PMID 35719155, 2022). "We used logistic regression to evaluate the effect of ESR and CRP on the diagnosis of malnutrition in GLIM-China." (PMID 36742004, 2022). "Our review also found that SPA is negatively related to levels of CRP and IL-6, two positive indicators of malnutrition." (PMID 36615707, 2022). "Alb can reflect inflammation and malnutrition, which explains the higher CRP, lower eGFR and lower Hb, UA, Ca, P, Mg in the low albumin group." (PMID 35983095, 2022). "Both CRP and albumin are widely used as acute inflammatory markers in clinical settings, and albumin is also used as a marker of malnutrition." (PMID 35094678, 2022). "In contrast, serum albumin levels are a parameter of malnutrition and decrease during a systemic state of inflammation through increased CRP synthesis." (PMID 35327399, 2022). "The main factors interacting with sRAGE for malnutrition development were Age, CRP and Sex (p = 0.003; p = 0.03 and p = 0.017, respectively)." (PMID 35883745, 2022). "Taken together, ESR and CRP had higher sensitivity to malnutrition than GLIM-China and PG-SGA, but the specificity was low, and the prediction of PG-SGA for malnutrition was better." (PMID 36742004, 2022). "Individuals with comorbidities, combined drug application, eczema history, malnutrition, elevated blood IL-6 and hs-CRP levels, older age, lower education level, worse medication literacy were more likely to have severe skin ADRs." (PMID 35505288, 2022). "This seems to be confirmed in our analysis, where only TLC and CRP have a significant effect on changing the probability of a patient being classified in the severe malnutrition group." (PMID 35276861, 2022). "Regarding serum markers for inflammation, we only detected a significant elevation of CRP in patients with severe malnutrition." (PMID 35719155, 2022). "In the ROC analyses both for mild or more severe malnutrition and for the moderate or more severe malnutrition, CRP had the highest AUC." (PMID 35160034, 2022). "Highly sensitive CRP levels are needed to examine the relationship between malnutrition and inflammation precisely." (PMID 35458190, 2022). "In contrast, patients older than 20 years old, where higher levels of CRP and immunoglobulins were found, also proved to be the most affected by malnutrition." (PMID 35379269, 2022). "Group 1 was characterized by lower serum albumin, prealbumin, Cr, K, and BUN, lower nPCR and higher hs-CRP levels, implying that high APR is associated with malnutrition and subclinical inflammation." (PMID 36346823, 2022). "Based on our results, a serum CRP of 32.62 mg/L seems to be an appropriate threshold of inflammation for severe malnutrition." (PMID 35276861, 2022).
malnutrition (continued). "In another prospective cohort study of community-dwelling Chinese subjects (median age: 72 years), high-sensitivity CRP cut-off levels of ≥0.32 mg/dl in men and ≥0.38 mg/dl in women were used for the diagnosis of malnutrition according to GLIM." (PMID 34282291, 2022). "Spearman rank correlation analysis was used to calculate the correlation coefficients between different specific indicators of malnutrition (adults: BMI and CRP; adolescents: Z-score) and WBC count after chemotherapy." (PMID 35967822, 2022). "The Glasgow Prognostic Score (GPS) has been reported as a parameter that elevated serum C-reactive protein (CRP) levels reflect a progression cancer stage, and decreased serum albumin levels are an indicator of malnutrition." (PMID 34519976, 2022). "Previous studies 32-34 have explored the prognostic factors for short-term all-cause mortality in elderly patients with HD include lower serum albumin, lower BMI, higher level of C-reactive protein (CRP), suboptimal initiation of HD, malnutrition and frailty." (PMID 34400900, 2021). "Our study found that the more severe the malnutrition, the higher the hypersensitive C reactive protein level." (PMID 34838083, 2021). "The M/E was highly negatively correlated to a number of comorbidities, malnutrition (as assessed by p-albumin), and inflammation (C-reactive protein)." (PMID 34743686, 2021). "Patients with malnutrition had higher levels of hs-CRP, neutrophil, and monocyte, but had a lower rate of complete revascularization." (PMID 34977188, 2021). "This suggests that the evaluation of visceral protein and CRP is essential in addition to the evaluation of malnutrition in patients with OD in the acute setting." (PMID 33673581, 2021). "This study also verified that the MIS has a good correlation with the malnutrition indicators hemoglobin and prealbumin and inflammation indicators CRP, IL-6, TNF-a and ferritin in PD patients." (PMID 33413177, 2021). "Several reports have shown that infection-driven inflammation correlates with markers of malnutrition and inflammation, such as CRP, WBC, Hb, and Cr in blood tests." (PMID 34851994, 2021). "The database we used included multiple inflammatory variables, including albumin adjusted for CRP level in order to take into account malnutrition with a view to ensuring model robustness." (PMID 34284784, 2021). "In fact, serum albumin, CRP, IL-6, and fetuin seem to be predictors of malnutrition, cardiovascular disease, and mortality in patients with advanced CKD." (PMID 34063052, 2021). "Based on the results of this review, patients with OD need to be assessed for visceral protein and CRP in addition to the assessment of malnutrition in the acute setting." (PMID 33673581, 2021). "The magnitude of difference between REEmeasured and REEpredicted was significantly higher in patients with higher CRP levels (r = −0.45, p = 0.033) and increased along with the degree of malnutrition (r = 0.42, p = 0.042)." (PMID 32727100, 2020). "This study, in consonance with earlier research, shows that systemic inflammation marked by elevated IL-6, CRP, and TNF-α levels is associated with functional decline and malnutrition, two central components of the frailty syndrome." (PMID 33166358, 2020). "In this study, the patients with moderate-severe malnutrition had higher counts of white blood cell and neutrophil and elevated serum levels of CRP, suggesting an active inflammatory state." (PMID 33041506, 2020). "Elevated levels of the inflammatory marker C-reactive protein (CRP) directly correlate to malnutrition, reduced fluid removal and mortality in RRT patients." (PMID 32521626, 2020). "The frequency of alcohol-induced cirrhosis, refractory ascites, hepatic encephalopathy, CRP > 20 mg/mL, and severe malnutrition was also higher in severe-sarcopenic patients." (PMID 33187310, 2020). "Malnutrition and inflammation were defined as low serum albumin (< 40 g/L) and high hs-CRP (≥ 28.57 nmol/L), respectively." (PMID 31048884, 2019).
malnutrition (continued). "It was reported that malnutrition assessed by serum albumin level was best predicted by hs-CRP level." (PMID 31048884, 2019). "The GPS, which takes into account albumin and CRP level values, showed that nearly 36% of patients had some degree of malnutrition or inflammation." (PMID 31583040, 2019). "In this study, patients with PAD had significantly higher CRP levels and lower albumin, total cholesterol, and iron levels, which are indirect indicators of malnutrition, inflammation, and atherosclerosis syndrome." (PMID 31349820, 2019). "GPS is a combination of CRP and albumin and is an exclusive index of systemic inflammation and malnutrition." (PMID 31096693, 2019). "The MIS was found to be superior to conventional predictors such as serum levels of C-reactive protein (CRP) as well as to other scales used to assess malnutrition among HD patients such as subjective global assessment." (PMID 30876391, 2019). "Considering that PTX3 is expressed in different tissues, including in the adipose tissue, this inflammatory biomarker seems to be more sensitive to inflammation-related malnutrition than CRP, IL-6, and TNF-α in this population." (PMID 31316299, 2019). "Usually, CRP correlates with the inflammation state, which is also the background of malnutrition, especially when chronic." (PMID 31443168, 2019). "In critically ill patients, CRP/ALB ratio reflects both inflammatory activation and nutritional deficiency, and has gradually been accepted as an emerging prognostic marker of morbidity and mortality." (PMID 31821367, 2019). "The current study found prealbumin in HIV-helminth coinfection to be a possible delineator between inflammation-induced reduction and true malnutrition, since in all cases of elevated CRP it remained higher, whereas albumin was lower." (PMID 30065944, 2018). "Normal nutritional group had a lower CRP level than the malnutrition group (0.8 ± 1.3 mg/dL vs. 2.7 ± 4.4 mg/dL, P = 0.017)." (PMID 30089153, 2018). "Recent studies have reported that NT-proBNP positively correlated with interleukin-6 and C-reactive protein and inversely correlated with serum albumin, so that NT-proBNP was considered a marker of inflammation or malnutrition." (PMID 29457529, 2018). "Systemic inflammation in patients with cancer causes an elevation in C-reactive protein (CRP), and decreases in serum albumin and total protein, which reflects malnutrition." (PMID 30513989, 2018). "NT-proBNP has recently been reported to correlate with inflammatory markers (interleukin-6 and C-reactive protein), a malnutrition marker (serum albumin), and protein-energy-wasting syndrome." (PMID 29457529, 2018). "(B) Serum Angpt-2 concentration in relation to the presence (I+ ve: CRP ≥ 5 mg/L) or absence (I− ve: CRP < 5 mg/L) of inflammation and presence (M+ ve: albumin < 30 g/L) or absence (M+ ve: albumin ≥ 30 g/L) of malnutrition." (PMID 30445969, 2018). "Inflammation was defined as those with hs-CRP ≥ 5 mg/L, while malnutrition was defined as those with serum albumin < 30 g/L." (PMID 30445969, 2018). "The degree of malnutrition (albumin), inflammation (CRP), arteriosclerosis (PWV), and fluid overload (BNP) were correlated well with the ECF/ICF ratio." (PMID 28099511, 2017). "In addition, inflammation (higher CRP levels) induced by underlying comorbidities and infections; such as diabetic foot and infections related to higher usage of catheter access; through increase muscle catabolism and suppression of appetite contribute to malnutrition and cachexia." (PMID 28491858, 2017). "It is known that malnutrition can lead to increases in inflammatory mediators such as pro-inflammatory cytokines and in the levels of the acute phase protein CRP." (PMID 26887418, 2016). "The adverse factors for malnutrition include disordered hormones, inflammatory cytokines (e.g., IL-6, TNFα, CRP), cigarette smoking, poor physical activity, and hypoxemia." (PMID 27669818, 2016).
malnutrition (continued). "Lorsque les valeurs de CRP étaient inférieures ou égales à 40 mg / L, la malnutrition est associée à un bas niveau plasmatique de sélénium (odds ratio (OR) = 3,25, intervalle de confiance à 95% (IC) de 1,39 à 7,63, p= 0,007." (PMID 27583075, 2016). "Albumin and CRP, both strongly related to inflammation-malnutrition, were shown to be poor predictors of malnutrition in this study." (PMID 27347538, 2015). "Les résultats ont montré une forte prévalence des états inflammatoires et/ou infectieux au cours de la malnutrition: 43% d’élévation simultanée de la CRP et de l'al-GRP ont été observés." (PMID 26161222, 2015). "Recipients were assessed based on serum albumin, cholesterol, or body mass index for the malnutrition factor and C-reactive protein level for the inflammation factor." (PMID 26194096, 2015). "A high ratio of hs-CRP/Alb indicates higher residual inflammation superimposed with malnutrition status." (PMID 25793462, 2015). "First, we used the ratio of hs-CRP/Alb as an indicial marker to evaluate the clinical outcomes, since it integrates the effects of both inflammation and malnutrition." (PMID 25793462, 2015). "Some authors indicate that nutritional assessment should also include analysis of biochemical nutritional parameters such as albumin and C-reactive protein (CRP) to account for inflammation in the establishment and maintenance of malnutrition." (PMID 24513015, 2014). "At CRP values less than or equal to 40 mg/L malnutrition increased the chance of low plasma selenium." (PMID 24886623, 2014). "When CRP values were less than or equal to 40 mg/L, malnutrition significantly increased the chance of low plasma selenium." (PMID 24886623, 2014). "• The interaction between CRP and malnutrition should be considered when interpreting plasma concentrations as an index of selenium status in patients with systemic inflammation as well as in the decision on selenium supplementation." (PMID 24886623, 2014). "Such as for the analysis of the outcome on admission, there was a significant interaction between CRP concentrations and malnutrition (P = 0.03)." (PMID 24886623, 2014). "This cutoff value for CRP derived from the statistical interaction between CRP values and malnutrition." (PMID 24886623, 2014). "Mean CIMT, malnutrition scores, CRP level and prevalence of carotid atheromatous plaques were significantly higher in patients with significant VC." (PMID 23360132, 2013). "The scale is based on the evaluation of 4 parameters: 2 markers of malnutrition: albumin and prealbumin, and 2 markers of inflammatory state: CRP and α1acid glycoprotein (AAG)." (PMID 22574625, 2012). "CRP/prealbumin levels >3 having a particularly higher mortality suggested that inflammation activity and malnutrition indicated a poor prognosis." (PMID 21714897, 2011). "Of all, 25.9% had albumin less than 3.5 g/dl who were suffering from malnutrition or were exposed to it, and 27.5% had CRP more than 1 mg/dL which is indicative of the existence of inflammation in these people." (PMID 21526100, 2010). "For esophageal cancer, a correlation has been shown between elevated serum CRP concentration and malnutrition with impaired immunity." (PMID 20673375, 2010). "The CRP/Alb ratio captures the bidirectional interplay between these two domains: systemic inflammation drives protein catabolism and reduces albumin synthesis, while malnutrition impairs immune competence, fueling inflammation." (PMID 40573094, 2025). "Which impose greater myelosuppressive burdens; second, advanced tumors are often accompanied by systemic deterioration, including malnutrition, systemic inflammatory response (elevated CRP), and organ dysfunction, all of which impair tolerance to chemotherapy toxicity." (PMID 41438123, 2025).
malnutrition (continued). "Both CRP and serum albumin (Alb) are useful markers for predicting morbidity and mortality in critically ill patients, as CRP is an effective marker of acute inflammation, whereas serum albumin (Alb) is an effective indicator of malnutrition status in critically ill patients." (PMID 40573094, 2025). "Therefore, inflammation is an essential factor in the development of malnutrition, as indicated by markers such as albumin, prealbumin, and C-reactive protein (CRP)." (PMID 40094974, 2025). "Secondly, CRP showed limited predictive value for identifying malnutrition." (PMID 41515189, 2025). "Therefore, it should be interpreted alongside inflammatory markers such as C-reactive protein (CRP) to distinguish malnutrition from hypercatabolic states." (PMID 41156516, 2025). "Likewise, serum CRP (since available in all participants) was also used to fulfill the etiologic disease burden/inflammation GLIM criterion for the diagnosis of malnutrition." (PMID 41228397, 2025). "In critically ill patients, the GLIM assessment using the maximum CRP level within 3 days after ICU admission may be useful for identifying patients with malnutrition risks." (PMID 40005032, 2025). "The purpose of the present study is to explore the utility of CRP in identifying malnutrition and to determine whether a nutritional assessment incorporating CRP criteria can effectively identify malnourished patients in the intensive care unit (ICU)." (PMID 40005032, 2025). "In another analysis of ESRD patients, hs-CRP predicted malnutrition better than IL-6." (PMID 40004669, 2025). "We also investigated whether a nutritional assessment combining the body mass index (BMI) criteria of the GLIM and the CRP criterion of the present study appropriately identified patients with malnutrition." (PMID 40005032, 2025). "In patients with malnutrition, increased CRP level is observed." (PMID 40137683, 2025). "According to the results, decreased levels of albumin (<3 g/dL) and hemoglobin (<11 g/dL), elevated homocysteine, CRP, IL-6 (>7.5 pg/mL), and IP-10 (>250 pg/mL) may attract medical processionals’ attention when diagnosing malnutrition." (PMID 40094974, 2025). "The partial mediation by CRP observed in our analysis supports a mechanistic pathway whereby malnutrition may contribute to fibrosis progression through heightened systemic inflammation." (PMID 41463388, 2025). "We investigated whether inflammation, assessed by CRP levels, acted as a mediator in the relationship between malnutrition and liver stiffness, adjusting for age and sex." (PMID 41463388, 2025). "HD patients with elevated serum CRP and reduced albumin levels are often described as having malnutrition–inflammation–atherosclerosis syndrome, which highlights the association between these factors and the progression of advanced atherosclerotic cardiovascular disease." (PMID 41149851, 2025). "Moreover, ALB has long been used as a representative marker of malnutrition; however, serum ALB levels are easily affected by inflammation, and therefore, serum ALB and C-reactive protein (CRP) levels are known to be negatively associated with each other." (PMID 39519547, 2024). "Admission CRP levels were also higher in the malnutrition risk group than in the non-risk group (p = 0.017), indicating more severe inflammation." (PMID 39091681, 2024). "In our findings, individual components were identified as frequent chemotoxicity risk factors, including malnutrition, frailty, hepato-renal functions, pro-inflammatory status (increased WBC or CRP), previous colorectal surgical histories, cancer stages, chemotherapy doses, and baseline HRQoL." (PMID 39061235, 2024). "Accordingly, malnutrition was significantly associated with BMI (P = 0.003), calf circumference (P < 0.001), weight loss (P < 0.001), MMSE score < 24 (P = 0.005), TUG test (P = 0.016), and CRP (P < 0.001)." (PMID 39097715, 2024).